LDHC (lactate dehydrogenase C)
Diseases named in the same sentence as LDHC in open-access papers (continued):
Sharing a sentence is not in itself a finding about the gene and the disease.
seminoma (1 paper, 2022). A radiosensitive malignant germ cell tumor found in the testis (especially undescended), and extragonadal sites (anterior mediastinum and pineal gland). "LDHC is specifically expressed in spermatocytic seminomas during the prophase of meiosis." (PMID 36408133, 2022).
testicular germ cell tumor (1 paper, 2022). A germ cell tumor arising from the testis. "Some cases of testicular germ cell tumors had a relatively high expression of LDHC, which may be due to undiagnosed normal testis elements in the tumors." (PMID 36408133, 2022).
cancer (32 papers, 2015 to 2026). A tumor composed of atypical neoplastic, often pleomorphic cells that invade other tissues. "This study supports the therapeutic potential of targeting LDHC to mitigate cancer cell survival and improve sensitivity to agents that cause DNA damage or inhibit its repair." (PMID 34050611, 2022). "Essentially, sperm-specific lactate dehydrogenase C (LDHC) is a glycolytic enzyme that was revealed to cause constitutive activation of the anaerobic pathway in cancers." (PMID 34249897, 2021). "Notably, screening performed to find novel cancer-associated immunogenic gene products allowed the identification of four cancer-restricted splice variants of testis Lactate Dehydrogenase C (LDHC) in several cancers." (PMID 34440480, 2021). "This approach represents a novel, effective, and safe proof-of-concept therapeutic strategy to target LDHC, with potential translational relevance as a standalone therapy or in combination with common anti-cancer drugs." (PMID 41599186, 2026). "Analysis of cancer cell-immune cell co-cultures revealed that tumor LDHC expression differentially regulates the expression of soluble inflammatory mediators through direct cell–cell contact and indirect interactions." (PMID 40108668, 2025). "We previously identified Lactate Dehydrogenase C (LDHC) as a promising anti-cancer target due to its role in regulating cancer cell genomic integrity." (PMID 40108668, 2025). "Looking at the cancer cells, we observed a reduction in the number of LDHC-silenced cancer cells expressing PD-L1, PD-L2 and CD80, and decrease in the cell surface expression of PD-L2, Gal-9, PVR, HLA-DR and VISTA." (PMID 40108668, 2025). "Using a 23-plex bead-based immunoassay, we found that knockdown of LDHC significantly increased the levels of cancer cell-derived GM-CSF, IFN-γ, MCP-1, and CXCL1, while reducing IL-6 and Gal-9 levels." (PMID 40108668, 2025). "Together, these findings suggest that silencing of LDHC in cancer cells disrupts multiple immune checkpoint signaling axes, resulting in enhanced T cell activity." (PMID 40108668, 2025). "For instance, TIGIT, TIM3 and VISTA expression were downregulated in direct co-cultures with LDHC-silenced cancer cells by 72 h, while CTLA-4 expression was reduced in indirect co-cultures." (PMID 40108668, 2025). "In this study, we explored the potential of targeting LDHC in cancer cells to impact anti-tumor immunity, proposing a novel dual approach to both target tumor cells and enhance the immune response." (PMID 40108668, 2025). "The inhibition of STAT3 not only reversed the unfavorable effect of LDHC silencing in the Her2-enriched cancer cells but also demonstrated significant anti-cancer activity when used as a single agent." (PMID 39001513, 2024). "Collectively, these analyses corroborate our previous findings of dysregulated cell cycle progression and reduced long-term cancer cell survival following LDHC silencing." (PMID 39001513, 2024). "Future studies are needed to decipher the impact of LDHC silencing on metabolic pathways in tumor cells and how these can be exploited in cancer therapy." (PMID 39001513, 2024). "The current studies focusing on LDHC in cancer, although limited in number, show great promise and warrant further investigation." (PMID 36814815, 2023). "Our findings strongly support the therapeutic potential of targeting LDHC to directly affect tumor cell survival or to improve treatment response to existing anti-cancer drugs." (PMID 36814815, 2023). "Molecularly, we observed that downregulation of LDHC dysregulates various cell cycle checkpoints, resulting in the accumulation of DNA damage and driving cancer cells towards mitotic catastrophe and ultimately cell death." (PMID 36814815, 2023). "We believe that LDHC holds great therapeutic potential to directly target cancer cells, sensitize cancer cells to DDR drugs, and induce specific anti-tumor immune responses." (PMID 36814815, 2023).
cancer (continued). "Herein, the high expression of LDHC in LUAD tissular samples reveals its cancer promoter roles in LUAD, which is substantiated by the poorer OS of LDH-C4-positive sufferers." (PMID 35814471, 2022). "Others have reported that LDHC promotes cancer cell proliferation, migration, and invasion in numerous cancer types." (PMID 34050611, 2022). "This is particularly important because LDHC is currently being considered as a target for cancer immunotherapy." (PMID 33565176, 2021). "The LDHC isoenzyme is an immunogenic germline-specific antigen that is re-expressed in a wide variety of cancer types." (PMID 33324565, 2020). "To date, there are no published data on the immunogenicity and targetability of the cancer testis antigen LDHC for cancer immunotherapy except for a Master’s thesis that is deposited in the public domain." (PMID 31932876, 2020). "To conclude, we demonstrate for the first time that LDHC exhibits immunogenicity and our findings warrant further study into the potential of LDHC as a novel therapeutic target for cancer immunotherapy." (PMID 31932876, 2020). "We found that LDHC levels were elevated in HCC tissues compared with non-cancer controls, and also highly expressed in stage I-IV HCC patients." (PMID 33035196, 2020). "This restricted expression pattern together with the important role of LDHC in cancer metabolism renders LDHC a potential target for immunotherapy." (PMID 31932876, 2020). "Another study on renal cell carcinoma patient samples revealed that LDHC expression level were significantly upregulated in cancer tissues and positively correlated with shorter progression-free survival." (PMID 31146503, 2019). "In the last few years, some studies have explored its role in cancer and found that in breast cancer cells LDHC promotes tumor invasion and migration." (PMID 31146503, 2019). "Our findings indicate that targeting cancer testis antigens such as LDHC and PRAME could provide novel approaches to both disrupt pro-tumorigenic intrinsic mechanisms and overcome immune evasion." (PMID 40108668, 2025). "Accordingly, gene silencing of LDHC using RNA interference (RNAi) or CRISPR-Cas9 may inhibit cancer cell metabolism and proliferation." (PMID 40270965, 2025). "Since we found that aberrant expression of LDHC in tumor cells impacts T cell activity and dysregulates the secretion of tumor-derived pro-inflammatory molecules, we sought to assess the effects of LDHC silencing on cytokine levels in cancer cell-PBL co-culture models." (PMID 40108668, 2025). "There was promising evidence suggesting that LDHC may be a potential therapeutic strategy for cancer." (PMID 40270965, 2025). "Notably, LDHC knockdown also resulted in lower levels of soluble Gal-9 in cancer cell monocultures and indirect co-cultures, which likely reduces its binding to the inhibitory immune checkpoint receptor TIM3, thereby enhancing T cell activation." (PMID 40108668, 2025). "Therefore, we investigated the tumorigenic effect of LDHC proteins on cancer cells by a co-culture model." (PMID 40270965, 2025). "In addition, we observed a significant increase in immune cell-mediated cancer cell killing following LDHC silencing in all cell lines." (PMID 40108668, 2025). "LDHC expression can be observed in various tumor types following transcriptional de-repression; however, its biological functions in cancer remain largely unknown." (PMID 39001513, 2024). "Given the key role of STAT3 signaling in cancer cell proliferation and survival, the question of whether the cell line-dependent regulation of this pathway could result in a divergent effect of LDHC silencing on tumor cell survival arose." (PMID 39001513, 2024). "Moreover, we demonstrated that reducing LDHC expression potentiates the efficacy of common anti-cancer drugs, illustrating the therapeutic potential of LDHC as a novel anti-cancer target for combination therapy in addition to single-agent therapy." (PMID 39001513, 2024).
cancer (continued). "LDHC activation in cancers may provide a metabolic rescue pathway in tumor cells by using lactate for ATP delivery." (PMID 37006626, 2023). "Moreover, the tumor‐specific expression of LDHC allows precise targeting of cancer cells with limited off‐target effects, which is an improvement over currently available cell cycle inhibitors that affect any dividing somatic cells." (PMID 34050611, 2022). "Given the role of a number of CTAs in maintaining genomic integrity during meiosis and in particular of SSX2, NXF2, and FMR1NB in cancer genomic instability, we investigated whether LDHC tumor re‐expression might be related to the latter." (PMID 34050611, 2022). "In 2016, a research team cataloged GNE-140 from a high throughput screening of two million compounds as having ability to inhibit LDHA, LDHB, and LDHC with IC50s in the nanomolar range, which could entirely block lactic acid production in cancer cells." (PMID 34944395, 2021). "Very little data are available on the role of LDHC in cancer." (PMID 31932876, 2020). "In this regard, gaining insight into the potential role of tumor-specific antigens, such as LDHC, in cancer metabolism could aid the development of specific inhibitors to circumvent the risk of adversely impacting normal cells." (PMID 33324565, 2020). "Based on the observations of LDHA- and LDHB-mediated cancer progression, we can speculate that LDHC could be involved in metabolic reprograming of cancer cells." (PMID 31932876, 2020). "Interestingly, we found that reduction of LDHC expression in the HLA-A*0201 positive cancer cells attenuated the T cell responses against LDHC, suggesting a plausible threshold of LDHC expression to elicit immune reactivity." (PMID 31932876, 2020). "However, the evidence for LDHC in peptide-based treatment of cancers is still insufficient." (PMID 40270965, 2025). "Moreover, we demonstrate that targeting LDHC augments the cytotoxic activity of DNA damage repair targeted therapy and hence may offer a novel anti‐cancer therapeutic strategy with minimal off‐target effects." (PMID 34050611, 2022). "Hence, altered expression of LDHC could be involved in maintaining an alternative energy source by contributing to the metabolic switch in cancer cells." (PMID 31932876, 2020). "Moreover, targeting LDHC would not only inhibit LDHC-mediated cancer progression and specifically eradicate LDHC positive tumor cells, but could also induce reversal of the acidic tumor microenvironment, thereby releasing anti-tumor immunity." (PMID 31932876, 2020). "Targeting LDHC could be a promising novel approach for cancer immunotherapy." (PMID 31932876, 2020). "Analyzing the expression of LDHs genes including LDHA, LDHB, LDHC and LDHD in all cancer types, we found that the expression of LDHA, LDHB and LDHD was higher than that of LDHC in pan-cancer." (PMID 38291366, 2024). "Lactate dehydrogenase C (LDHC), an anticancer target with tumor-specific expression and immunogenicity, is a cancer testis antigen (CTA)." (PMID 35885460, 2022). "Hence, our team speculated that the cancer promoter LDHC molecules were released from exosomes to the outside of cells to facilitate the proliferative ability and growth of oncocytes, and that LDHC might exert an effect on the micro-environment of cancer metabolic activity." (PMID 35814471, 2022). "In line with this, two studies to date demonstrate that enhanced expression of LDHC induces epithelial-to-mesenchymal transition, matrix metalloproteinase-9 (MMP9) expression and promotes cancer cell migration and invasion." (PMID 31932876, 2020). "Moreover, LDHC was found to promote tumor cell survival and invasion by maintaining the NAD+/NADH balance, which helps cancer cells resist oxidative stress and survive in harsh microenvironments." (PMID 40270965, 2025). "Moreover, the change in the expression of TUBA1C, PRDX4, LDHC, C7, and KNG1 due to NVA-AA treatment corroborated with the sensitivity provided by CTRP drugs to cancer cells." (PMID 37719007, 2023).
cancer (continued). "Except for LDHA and LDHB, LDHC and LDHD are expressed in various cancers." (PMID 37547725, 2023). "Moreover, combination treatment of LDHC silencing with DDR drugs such as cisplatin and olaparib significantly increased DNA damage and reduced cancer cell survival." (PMID 36814815, 2023). "LDH-C4 is not cancer-type specific, and most studies suggest that LDHC/LDH-C4 can be used as a prognostic indicator of tumors." (PMID 36408133, 2022). "Role of LDHC and LDHD has not been fully explored in cancers; a recent loss-of-function study in LDHD identified two different homozygous variants of LDHD resulting in enzymatic loss-of-function and increased concentrations of D-lactate." (PMID 31146503, 2019). "Moreover, our findings suggest that LDHC may exert its effects on genomic integrity and cancer cell survival independent of LDHA/B as we did not observe any compensatory increase in LDHA/B expression for the loss or reduction of LDHC expression." (PMID 34050611, 2022). "Furthermore, LDHA expression is not altered in LDHC high versus LDHC low expressing cancer cells (unpublished data), suggesting that the difference in peptide-specific T cell responses in LDHC high versus LDHC low expressing cells might not be affected by cross-reactivity with LDHA cognate peptides." (PMID 31932876, 2020). "Overall, STAT3 inhibition reversed the unfavorable effects of LDHC silencing in HCC-1954 cells and reduced the cancer cell survival of siCTRL cells, indicating that HCC-1954 cells do not benefit from LDHC-targeted therapy but may benefit from monotherapy with STAT3 inhibitors." (PMID 39001513, 2024).
tumor (24 papers, 2010 to 2026). "Furthermore, LDHC expression in renal tumor tissue is associated with shorter survival, further supporting its role in tumor progression and poor clinical outcome." (PMID 40108668, 2025). "Aberrant tumor LDHC expression is associated with T cell dysfunction." (PMID 40108668, 2025). "In this respect, we and others have shown that LDHC is expressed in various tumor types, can elicit anti-tumor cellular immune responses, is associated with worse clinical outcomes, and supports tumorigenesis and progression through multiple biological processes." (PMID 39001513, 2024). "Why might LDHC be a risk factor for some tumor types but a protective factor for prognoses of other tumor types (HNSCC and CESC) remains unclear?" (PMID 36408133, 2022). "However, reports on the detailed mechanism underlying LDHC’s involvement in tumor development are scarce." (PMID 36408133, 2022). "Indeed, the inhibition of STAT3 following LDHC silencing restored the loss-of-tumor cell survival." (PMID 39001513, 2024). "As a key regulator of aerobic glycolysis, aberrant LDHC expression in tumors is presumed to increase the lactate levels in the tumor microenvironment." (PMID 40108668, 2025). "LDHC is the first lactate dehydrogenase isoform restricted to tumor cells and prefers lactate as a substrate compared with other LDH isoenzymes." (PMID 40270965, 2025). "TIMER AND TIDE deconvolution methods were used to investigate the relationship between tumor LDHC expression, immune cell infiltration and T cell dysfunction." (PMID 40108668, 2025). "In tumor cells, LDHC contributes to metabolic reprogramming by driving aerobic glycolysis and promotes tumor cell invasion, migration, and proliferation through activation of the PI3K/Akt/GSK-3B signaling pathway." (PMID 40108668, 2025). "This discrepancy suggests that the immunomodulatory effects of tumor cell LDHC expression are largely mediated through direct cell–cell interactions rather than soluble factor signaling." (PMID 40108668, 2025). "Tumor LDHC expression is regulated by the Sp1 and CREB transcription factors, in addition to promoter CpG island hypomethylation." (PMID 40108668, 2025). "Both methods also indicated that LDHC expression was positively correlated with tumor purity, suggesting that tumor cells are likely the main source of LDHC in the tumor microenvironment." (PMID 40108668, 2025). "In this study, we explored the role of LDHC expression in tumor cells in the tumor immune microenvironment, particularly in the intricate dynamic interplay between tumor cells and immune cells that drive immune escape." (PMID 40108668, 2025). "Next, we co-cultured LDHC-silenced tumor cells and their control counterparts with peripheral blood lymphocytes and assessed IFN-γ secretion using the ELISpot assay." (PMID 40108668, 2025). "LDHC has been shown to promote tumor growth and metastasis of lung adenocarcinomas via activation of the PI3K/Akt/GSK-3β oncogenic-signaling pathway." (PMID 38596293, 2024). "Few studies have shown that LDHC expression enhances tumor cell migration and invasion and promotes xenograft tumor growth and metastatic propensity." (PMID 39001513, 2024). "The promoter methylation level of LDHC was significantly lower than that of the normal group in 2 tumor groups, but significantly higher than that of the normal group in 3 tumor groups." (PMID 38291366, 2024). "Our findings indicate that targeting of LDHC likely interferes with tumor cell survival by a multitude of mechanisms affecting genomic stability, including dysregulated cell cycle progression." (PMID 34050611, 2022). "The cancer testis antigen (CTA) lactate dehydrogenase C (LDHC) is a promising anticancer target with tumor‐specific expression and immunogenicity." (PMID 34050611, 2022). "LDHC is expressed in serum and serum exosomes of tumor patients, with serum LDHC positivity rates of 91.66%, 68%, and 65% in BC, HCC, and LUAD, respectively." (PMID 36408133, 2022).